CD4 (CD4 molecule)
Diseases named in the same sentence as CD4 in open-access papers (continued):
Sharing a sentence is not in itself a finding about the gene and the disease.
tumor (continued). "However, CTX chemotherapy creates an environment that drives robust effector differentiation of adoptively transferred tumor-specific CD4+ T cells, giving rise to polyfunctional CD4 effector cells capable of responding to exogenous IL-7." (PMID 28939858, 2017). "Similarly, IL-21 was able to inhibit tumour-mediated FOXP3 induction in naïve CD4 T cells and restore their proliferative capacity." (PMID 28239749, 2017). "Also, the presence of immunosuppressive cytokines and that of suppressive tumor-associated cells are common mechanisms by which tumors block the induction and establishment of effective CD8+ cytotoxic T lymphocytes (CTLs) or CD4+ T helper cells." (PMID 27585790, 2017). "However, some CD4+ T cells have been classified as effector cells capable of the direct or indirect killing of tumor cells." (PMID 28635644, 2017). "MHC-II+ epithelial cells can present antigen to CD4+ Th cells and thus, promoting the expression of HLA-DR in tumor cells with HDACi, may promote anti-tumor immunity and tumor suppression as an adaptive response." (PMID 29371976, 2017). "Human monocyte-derived DC pulsed with HHP-killed tumor cells displayed increased expression of maturation-associated molecules and pro-inflammatory cytokine production which resulted in stimulation of IFN-γ-producing CD8+ and CD4+ T cells in vitro." (PMID 28187172, 2017). "It has been further observed that tumor cells might evade immune system surveillance through the interaction between PD-L1 and PD-L2 with their receptor PD-1, which is expressed on CD4 and CD8 T-cells, Tregs, B-cells, and natural killer (NK) cells." (PMID 28680882, 2017). "Therefore, we evaluated the paired immunologic expression of CD8+ lymphocytes, CD4+ lymphocytes, Foxp3+ lymphocytes, and the Galectin-9/Tim-3 pathway in the tumour microenvironment between primary and recurrent NPC from 95 patients." (PMID 28871094, 2017). "Therefore, B16-OVA tumour-bearing mice were treated with 5 × 105 of each day-10 or day-20 in vitro expanded CD4+ Th1 cells and/or CD8+ CTLs." (PMID 29114389, 2017). "Moreover, no change in the expression of FoxP3 transcription factor was observed in tumor-infiltrating CD4+T cells in 4T1HA and RencaHA tumor-bearing mice." (PMID 28052005, 2017). "In addition, the number of CD3+CD4+CD25+Tregs in PBMCs from the tumor-bearing BALB/c mice immunized with STAT3-blocked HCC vaccine decreased." (PMID 29115974, 2017). "Tumor-transplanted mice had measurable CD4+ T cells and substantial CD8+ T cells present." (PMID 29050201, 2017). "Here, we evaluated the impact of expressing a range of HLA‐I‐restricted tumour‐specific TCRs with different affinities for cognate antigen on CD4+ T cells and compared the functional efficacy of these redirected CD4+ T cells with CD8+ T cells expressing the same TCRs." (PMID 27324616, 2017). "Despite of a paucity of IL-7 in the immune milieu, CTX preconditioning allowed adoptively transferred naïve tumor-specific CD4+ T cells to undergo effector differentiation and regain IL-7Rα expression, giving rise to IL-7-responsive polyfunctional CD4+ effector cells." (PMID 28939858, 2017). "But other, HLA class I-independent effector mechanisms might step in, such as CD4+ tumor-reactive T cells with direct effects on HLA class II-positive and indirect effects on HLA class II-negative tumors as well as natural killer cells." (PMID 28423700, 2017). "This may inhibit the commitment of näive T cells towards the T helper (CD4+) phenotype and is associated with an enhanced commitment of näive T cells towards a CD8+ phenotype, which would have an anti-tumor effect." (PMID 28977830, 2017). "As both CD4+ and CD8+ T cell responses are believed to be beneficial for tumour clearance, it could be advantageous to include HLA‐I‐redirected CD4+ T cells in adoptive cell transfer regimens in addition to CD8+ T cells." (PMID 27324616, 2017).
tumor (continued). "Additionally, in vivo viral infection in mice bearing lung cancer showed reduced tumor growth, increased numbers of CD8+ and CD4+ T cells infiltrating the tumor, and increased mouse survival." (PMID 29091951, 2017). "By comparing the percentages of T cell subpopulations isolated from tumor-bearing mice in the different experimental groups, we observed by flow cytometry that more CD4+ and CD8+ T cells infiltrated into the tumor site in the LM4Δhly::E7 and LM4Δhly::esat-6 groups compared with the PBS group." (PMID 28706878, 2017). "IL17 derived from a subset of CD4+ T helper cells has also been shown to promote anti-tumor immune responses through the recruitment of dendritic cells and cytotoxic cells in several murine tumor models." (PMID 28883015, 2017). "Hence, an attractive solution to this problem would be to engineer CD4+ T cells so that they can recognize HLA‐I restricted cancer peptides and provide help directly at the tumour site." (PMID 27324616, 2017). "In summary, peripheral CD4+ naïve/memory ratio may provide an independent predictor of tumor progression in NSCLC patients." (PMID 29137371, 2017). "Among these cytokines, IL-6 had the highest concentration, indicating that IL-6 secreted by CD4+ T cells may play a role in the interaction with tumor cells." (PMID 28846080, 2017). "We were intrigued to find out whether differential tumour responses would be observed in ACT using CD4+ Th1 cells and/or CD8+ CTLs that had been cultured for different periods of time." (PMID 29114389, 2017). "Expression of HLA class II may be involved in establishment of the CD4+ T cell infiltrate in the cHL tumor microenvironment, however this is difficult to assess as it probably occurs early in disease pathogenesis." (PMID 28334025, 2017). "However, slightly and statistically significant (*P⩽0.05 and ** P⩽0.005, t-test), accelerated tumour growth was noted especially in CD4-depleted animals." (PMID 28300057, 2017). "Dendritic cells could then pick up and present the tumor antigens to CD4+ and CD8+ T cells resulting in a systemic cell-mediated immune response." (PMID 29037259, 2017). "To visually observe tumor-infiltrating Tregs in xenografts, we detected CD4 and Foxp3 expression to identify Tregs in tissue section of tumors by double immunofluorescence stains, positive expression of Foxp3 was used to locate Tregs cells because CD25 is not specific for these cells." (PMID 28472762, 2017). "A dramatic fall in the CD4+ T lymphocyte level greatly influenced the anti-tumor activity that may lead to a fast progression of HCC." (PMID 29262635, 2017). "The proportion of CD4+IL-17+ Th17 cells was significantly higher in the different HCC tumor stage groups than in the control group; moreover, the proportion of CD4+IL-17+ Th17 cells was significantly higher in the advanced (stage III-IV) HCC group than in the early (stage I-II) HCC group." (PMID 28796055, 2017). "Foxp3+ Tregs is a highly immunosuppressive subset of CD4+ T cells that is critical in s uppressing proliferation and cytokine production of other T cells, inhibiting tumor-specific immune responses and maintaining peripheral immune tolerance in cancer patients." (PMID 27974689, 2017). "Thus naive CD4+ T cells can be converted to functional Tregs in vitro by exposure to TI DCs and tumor CM." (PMID 28290464, 2017). "During the course of the disease or after treatment, it is crucial to assess whether an increase in the CD4 population results from an expansion of the tumor cell population or of reactive T lymphocytes." (PMID 28912774, 2017). "Experiments to determine how CD4+ T cells mediate inhibition of TSC tumor growth are ongoing as are experiments to determine whether antibodies mediate inhibition of TSC tumor growth by neutralization of inhibin-α or by complement-dependent cytotoxicity." (PMID 28428886, 2017). "This may be a particularly important limitation in the ability to detect self-antigen and tumor-specific CD4+ T cell populations." (PMID 28314956, 2017).
tumor (continued). "CD4 cells actively participate in shaping anti-tumor immunity." (PMID 27832300, 2017). "In addition, CD4+ T cells can remodel the tumor microenvironment, creating an immune milieu that is hostile to tumor growth." (PMID 28939858, 2017). "Finally, an anti-CD8 depleting mAb was administered to tumor-bearing mice together with combined anti-CD4/anti-PD-1 mAb therapy." (PMID 29070883, 2017). "To determine whether the ability to recognize tumor antigens is responsible for the enhancement of antitumor immunity in this model system, we transferred ex vivo—expanded CD4+ T cells from OT-II transgenic mice into sublethally irradiated lymphopenic mice." (PMID 28854279, 2017). "Specifically, CD4+ T cells are major players in orchestrating immune responses to tumor cells." (PMID 27935860, 2017). "Notably, HTM without detectable solid tumor formation (BT474, red symbols) at the end of the experiments showed a tendency towards a higher CD4 T-cell fraction in the spleen compared to tumor-bearing mice." (PMID 27835865, 2017). "Furthermore, the virus itself can stimulate different immune cells including CD4+ T cells, natural killer (NK) cells, and macrophages, all of which can mount an anti-tumor response." (PMID 28536354, 2017). "As consequence, indirect anti-tumor effects of tumor antigen specific CD4+ T cells could be analyzed with this cell line." (PMID 28301575, 2017). "In addition, the drop/rebound IL-7Rα expression pattern in tumor-specific CD4+ T cells is likely driven by TCR signaling alone." (PMID 28939858, 2017). "A statin-induced increase in CD4+CD25+ regulatory T cells (Tregs) may impair the host antitumor immune response through suppressing the tumor specific effector T cell response, which may lead to an increased risk of cancer." (PMID 29088876, 2017). "Indeed, in the circulating T cells from SS patients, expression of NKp46 is restricted to the clonal Vß CD4+ population identifying the tumor cells." (PMID 28912774, 2017). "Possibly, this could be explained by an ablation of dominant Treg clones in tumor milieu and their replacement by rare thymus-derived Treg clones or conversion of certain CD4+Teffs." (PMID 28638937, 2017). "CD4+ T cells can act as effector cells to execute direct tumor lysis through granzyme B11,12." (PMID 28939858, 2017). "Therefore, vaccine success can be theoretically determined by the changes in the ratio of the ICOS (anti-tumor effector activity) to FoxP3 (pro-tumor immunosuppressive activity) expression on CD4+ T-cells." (PMID 28304339, 2017). "This variation may be explained by the fact that CD4+ represents not only tumor-reactive Th cells but also Treg cells." (PMID 28791250, 2017). "Thus, we analyzed the percentage of FoxP3+ cells in the CD4+ T cells from the spleens of the different treatment groups in non-tumor bearing mice." (PMID 28029653, 2017). "Moreover, transphagocytic CD4+ T cells induce protective anti-tumour immune responses by priming CD8+ T cells, highlighting the potential of CD4+ T cells as a tool for cancer immunotherapy." (PMID 29147022, 2017). "Acute tumor-directed immune responses involving the Th1 CD4+T-helper cells enhance antitumor immune responses by INFγ secretion, which in turn induces activation of macrophage cytotoxic activity and, consequently, inhibits tumor development." (PMID 28927416, 2017). "The PBT anti-tumor effect was accompanied by an increase in granzyme B+, IFN-γ+ CD8+ T-cells and a decrease in immunosuppressive tumor infiltrating cells including Gr-1+CD11b+ myeloid derived suppressor cells (MDSCs), CD4+CD25+ Tregs, and CD206+F4/80+ M2 macrophages." (PMID 29137411, 2017). "Furthermore, our data indicated that the inhibition of PD-1+ and Tim-3+ significantly enhanced tumor-infiltrating CD4+/CD8+ T-cells IFN-γ secretion in patients with GC compared with the control group." (PMID 29213216, 2017). "DTA-1 treatment of tumor-bearing mice had a different impact on CD4+Teffs and Tregs." (PMID 28638937, 2017).
tumor (continued). "In a Th1 microenvironment, proinflammatory cytokines (e.g., IL-6, IL-1α, and IL-1β) may contribute to tumour eradication by attracting leucocytes from the circulation and by increasing CD4 + T cell activity." (PMID 29089667, 2017). "Importantly, after co-incubating these tumor cells with POM-1, the CD39 inhibitor, tumor-induced inhibition of CD4+ and CD8+ T cell proliferation was alleviated and CTL- or NK cell-mediated cytotoxicity increased." (PMID 28690614, 2017). "Moreover, FOXP3+ CD4+ Treg cells also influence effector T cell function in the microenvironment within tumor." (PMID 28545567, 2017). "The composition of tumor-infiltrating lymphocytes in these experimental tumors was lower in CD8+ T cells in mice deficient in HIF-1α in T cells, and there was a diminished CD8+-to-CD4+ T cell ratio." (PMID 29136509, 2017). "Notably, TIM3 is expressed on tumor-infiltrating Tregs (CD4+, CD25+, Foxp3+), which suppress CD8+ cytotoxic T-cells (CTLs)." (PMID 28100240, 2017). "In the same murine model, CD137 signaling improved expression of pro-inflammatory cytokines and cytotoxic effector molecules in tumor-specific CD4 T cells, coincident with upregulation of Eomes and Tbox; these cells were able to kill virus-induced tumor cells in vivo." (PMID 28167943, 2017). "Tumor-infiltrated CD4+ T cells and CD8+ T cells were monitored using flow cytometry." (PMID 28537894, 2017). "Interestingly, based on the notion that responding T cells preferentially compartmentalize into the liver, the presence of CD4+ CTL was investigated in tumor specimens." (PMID 28289418, 2017). "CD4+Th subsets play an important role in tumor progression but their expression characteristics and clinical significance in human tumor microenvironment remains unclear." (PMID 28061450, 2017). "Given the substantial IL-17 production from CD26high T cells, we postulated that CD26 expression on CD4+ T cells might correlate with a more stem cell-like lymphocyte with enhanced tumor regression." (PMID 29213079, 2017). "The assessment of global TCR complexity revealed that DTA-1 treatment in case of dLN increased overall diversity of both Tregs and CD4+Teffs, but in the tumor, only diversity of Tregs—mainly those of low abundance—increased, while the diversity of Teffs decreased." (PMID 28638937, 2017). "It is plausible that Cbx3/HP1γ-insufficient CD8+ effector T cells may alter the tumor microenvironment thus preventing CD4+ Treg infiltration." (PMID 28220815, 2017). "Finally, levels of tumour cell cytotoxicity achieved were compared using EpCAM BiTE to activate purified CD4+ and CD8+ subsets." (PMID 28634161, 2017). "The level of Foxp3 expressing CD4+ Tregs is a critical component in suppressing tumor immunity." (PMID 28496193, 2017). "In a previous study, the authors reported that oncolytic virotherapy overcomes systemic tumour resistance to immune checkpoint blockade, due to the virus-induced inflammatory response which coincided with distant tumour infiltration of tumour-specific CD4+ and CD8+ T cells." (PMID 28345650, 2017). "In bortezomib-treated 4T1HA tumor-bearing mice, CD4+T-cells showed increased IL-2 production, CD11c+ dendritic cells showed increased IL-12 and IL-15 production, and HA-specific activated CD8+T-cells showed enhanced expression of IFNγ, granzyme-B and transcription factor eomesodermin." (PMID 28052005, 2017). "Additionally, PD-1-PD-L1 blockade in combination with Tim-3-Tim-3-L blockade further enhanced the capacity of tumor-infiltrating CD4+ T-cells to produce IFN-γ as compared with anti-PD-1-mAbs group (p = 0.0398) or anti-Tim-3-mAbs group (p = 0.0027)." (PMID 29213216, 2017). "Interestingly, the superior therapeutic effect of combined mCelyvir and ICOVIR5 was associated with a higher tumor infiltration of CD8+ and CD4+ T lymphocytes, suggesting a main role of immune system in efficacy of Celyvir." (PMID 28525366, 2017).
tumor (continued). "We previously demonstrated that in addition to generating an antigen-specific immune response, Listeria monocytogenes (Lm)-based immunotherapy significantly reduces the ratio of regulatory T cells (Tregs)/CD4+ and myeloid-derived suppressor cells (MDSCs) in the tumor microenvironment." (PMID 28807056, 2017). "Based on these data showing the potential importance of CD4+ T cells combined with Th2-related antitumor cytokine interactions in tumor clearance, we investigated how these diverse mechanisms interact with periodically pulsed therapies to dictate the antitumor function in this setting." (PMID 29250133, 2017). "Moreover, deletion of Tgfbr1 and Pten in murine epithelia activated HIF-1α, CD73 and subsequently induced A2AR overexpression in tumor infiltrating immune cells, accumulating immunosuppressive CD4+ Foxp3+ Tregs in the stroma of tumors." (PMID 28592285, 2017). "Further studies revealed that the level of CD4+CD25+ Treg cells was closely related to tumor size." (PMID 28796055, 2017). "Tumor cells with MHC-II expression can be eliminated by directly cytotoxic CD4+ T cells." (PMID 28635644, 2017). "In these models, we observed that Il9 mRNA expression and IL-9 protein secretion were reduced in tumour-infiltrating CD4+ T cells (TILs) or in CD4+ T cells from tumour-draining lymph nodes (TDLN) of Irf8f/fCd4cre mice compared to those of WT or Irf8+/+Cd4cre mice." (PMID 29233972, 2017). "Additionally, tumour samples showed a significant increase in the proportion of CD4+ T helper cells when compared to normal tissue, suggesting the activation of a systemic immune response to disease progression." (PMID 28447602, 2017). "Naive CD4+ T cells adhered to the tumor slices in proportion to the number of CCL18+ TAMs." (PMID 28290464, 2017). "Co-transferring day-20 CD4+ Th1 cells led to complete tumour remission in 40% of the mice." (PMID 29114389, 2017). "Interestingly, the superior therapeutic effect of the combined therapy was associated with a higher tumor infiltration of CD8+ and CD4+ T cells." (PMID 28525366, 2017). "Tumor CM on its own without DCs did not induce Treg differentiation of naive CD4+ T cells, but PB pDCs caused Treg differentiation when tumor CM was added." (PMID 28290464, 2017). "An increased number of CD4+FOXP3+ Tregs correlates with poor prognosis in NSCLC suggesting that differentiation of CD4+ to CD4+FOXP3+ cells may contribute to tumor escape." (PMID 28402937, 2017). "Our study suggests that high PD-1 expression on human CD4 effector cells identifies a population of exhausted effector cells that are enriched in malignant cancer and serve a crucial role in the context of inflammation and anti-tumor responses in GBM." (PMID 28880903, 2017). "Naturally occurring tumour‐specific HLA‐II‐restricted CD4+ T cells and those engineered to express HLA‐I‐restricted tumour TCRs have been reported to exhibit a mainly Th1 phenotype, where cells typically produce IFN‐γ, TNF‐α and IL‐2 but not IL‐4, IL‐5 or IL‐10." (PMID 27324616, 2017). "Moreover, CIK subsets contain regulatory T cells (Treg, CD4+ CD25+) that can suppress the immune function of the tumor." (PMID 29348890, 2017). "Indeed, a secondary response to RT is the release of endogenous tumor antigens via apoptotic or necrotic cell death, which are captured by DC, processed, and presented to CD4+ and CD8+ T cells." (PMID 28134800, 2017). "However, at least for most SV40 induced mouse tumors CTLs in combination with CD4+ helper cells are the major players in an effective anti-tumor response in BALB/c as well as in C57BL/6 mice." (PMID 28978072, 2017). "Hussain and Paterson showed in tumor-bearing mice that CD4 + CD25+ Tregs secreting transforming growth factor-β and the anti-inflammatory cytokine IL-10 are preferentially induced in mice vaccinated with Lm-E7, emphasizing the complexity of Lm-based immunotherapy." (PMID 28588899, 2017).